ICAM1 (intercellular adhesion molecule 1)
Diseases named in the same sentence as ICAM1 in open-access papers (continued):
Sharing a sentence is not in itself a finding about the gene and the disease.
infection (442 papers, 2005 to 2026). The state of being infected such as from the introduction of a foreign agent such as serum, vaccine, antigenic substance or organism. "We also observed that ICAM-1, a vascular adhesion molecule associated with endothelial inflammation, was significantly elevated in unvaccinated dogs early after infection, with minimal expression in vaccinated animals." (PMID 41159782, 2025). "Positive immunostaining for ICAM-1 in PNEs, suggests susceptibility to infection by major group RV serotypes." (PMID 40916026, 2025). "In this paper, we show that using the pair Swiss Webster mice + Y strain of T. cruzi, lovastatin was able to prevent the increase in macrophage number and ICAM-1 levels in the brain tissue caused by the acute infection." (PMID 38785783, 2024). "As target cells, CHO-LFA-1 express lymphocyte function-associated antigen 1 (LFA-1), which binds ICAM-1 on effector cells to stabilize cell-to-cell contact and induces the formation of a virological synapse from which infection occurs." (PMID 37375521, 2023). "We demonstrated that IL-33 induced an antiviral signature in MCs but rather than providing protection against HRV infection, IL-33 increased the infection of MC by HRV by causing upregulation in ICAM1, the receptor used by HRV16 for cellular entry." (PMID 36366528, 2022). "Paradoxically, increased expression of ICAM-1 also seems to enhance the susceptibility to infection that is primarily viral." (PMID 35316427, 2022). "Such reactions were indicative of the bafilomycin A1 potential to hinder RV14 infection by obstructing the RV RNA entrance into endosomes and also by decreasing the ICAM-1 expression in the associated epithelial cells." (PMID 33937285, 2021). "HRV-A16 infection also caused an increase in ICAM-1, the receptor for the major group of HRV including HRV-A16." (PMID 32637364, 2020). "This is the first report to demonstrate that enhancing ICAM‐1 expression increases susceptibility to RV14 infection in HNE cells obtained from allergic subjects." (PMID 27957326, 2016). "Further, infection of the endothelium with Semliki Forest virus caused infiltration of the CNS by LFA-1+/Mac-1+ CD8+ T cells followed by a local increase in ICAM-1 expression and BBB breakdown." (PMID 23133375, 2012). "In their study, erythromycin reduced the supernatant RV14 titers, RV14 RNA, the susceptibility to RV14 infection, and the production of ICAM-1 and cytokines which was upregulated by RV14." (PMID 22719178, 2012). "Infection of epithelial cells by Haemophilus influenzae (a common organism in COPD) increases susceptibility to infection by RV, possibly by up-regulation of ICAM-1." (PMID 22420941, 2012). "Clarithromycin, by inhibiting the production of intracellular adhesion molecule ICAM-1 and secretion of IL-6 and IL-8, significantly influences the pathophysiological changes associated with infection caused by rhinovirus (RV)." (PMID 22969171, 2012). "The expression of ICAM-1 on neuronal cells has been reported on cholinergic airway nerves supporting our hypothesis that airway neurons are directly susceptible to infection." (PMID 40916026, 2025). "This structural damage is associated with increased expression of ICAM-1 and serotonin, which may play roles in the immune response and tissue remodeling during infection." (PMID 40743275, 2025). "The higher ICAM1 protein level at the plasma membrane of keratinocytes facilitates lymphocyte function-associated antigen 1-dependent T cell adhesion and expression of gC during infection increases VZV spread to peripheral blood mononuclear cells." (PMID 38909022, 2024). "In this study, it was confirmed that Vero cells indeed do not express the ICAM1 receptor and it was explored whether stable expression of human ICAM1 on the surface is sufficient to create a Vero cell line, susceptible to infection with HRV." (PMID 36298792, 2022).
infection (continued). "It is reasonable to speculate that with the activation of ICAM-1, the risk of associated secondary infection may also increase." (PMID 36248845, 2022). "Next, we measured neutrophil counts in the lung homogenates and bronchoalveolar lavage fluid (BALF) to determine whether the increased ICAM-1 response to lasR mutant infections at 2 days p.i was also associated with increased lung neutrophilic infiltration." (PMID 33690714, 2021). "Our observations of ICAM-1 modulation in vitro therefore led us to ask whether lasR mutant infections were also associated with increased airway ICAM-1 expression in vivo." (PMID 33690714, 2021). "Furthermore, TNF-α-induced ICAM-1 expression associated with monocyte adhesion to HPAEpiCs was attenuated by infection with adenovirus (adv)-HO-1 or incubation with CORM-2." (PMID 30934992, 2019). "That the X4 tropic virus causes increased expression of ICAM-1 is important given this protein’s role in recruiting other immune mediators leading to a sustained inflammatory response as well as its potential to propagate cellular infection." (PMID 26930653, 2016). "Furthermore, erythromycin, a clinically used macrolide antibiotic, reduces the supernatant RV14 titer, RV14 RNA levels, susceptibility to RV14 infection, and production of ICAM-1 and pro-inflammatory cytokines." (PMID 22966430, 2012). "Overall, these data show that, upon infection, the development of cerebral trypanosomiasis is associated with the recruitment of inflammatory monocytes to the brain vasculature, most of which express ICAM1, and the infiltration of CD4+ T cells into the brain parenchyma." (PMID 35787830, 2022). "The first mechanism by which PM2.5 exposure may increase susceptibility to infection is by the promotion of bacterial adhesion to epithelial cells by the upregulation of the expression of the intercellular adhesion molecule-1 (ICAM-1, a glycoprotein on the cell surface)." (PMID 35270217, 2022). "Furthermore, confocal pictures revealed a variation in surface ICAM-1 distribution: a ‘punctuate’ organization with a loss of ‘cap’ distribution occurred, confirming that a reshaping of the plasma membrane arose because of the infection." (PMID 29899248, 2018). "However, increased RV14 replication was observed in the nasal epithelial cells obtained from allergic subjects, which might be partly attributed to the association of RV14 infection with increased ICAM‐1 expression and the increased number of acidic endosomes." (PMID 27957326, 2016). "Infection with T. gondii enhances ICAM-1 expression on endothelial surfaces, as confirmed in our study." (PMID 40141288, 2025). "Since TNF-α can stimulate ICAM-1 expression, we evaluated the infection rate of HBMEC and HUVEC in the presence of TNF-α." (PMID 40141288, 2025). "According to the infection status, both markers showed further upregulation in p24+ macrophages compared to their p24- counterparts, with ICAM-1 increasing by 1.1-fold and LFA-1 by 1.8-fold." (PMID 41322423, 2025). "Despite transcriptional changes observed within 4 h post-infection, ICAM-1 protein levels were measured 24 h post-infection." (PMID 40141288, 2025). "Upon infection, the expression of ICAM-1 and MHC-I was upregulated in infected young and infected adult mice but remained unchanged in infected aged mice, suggesting that aged AECs did not respond to HSV-1 infection." (PMID 40732672, 2025). "This response helps control the infection, but prolonged ICAM-1 upregulation can lead to chronic inflammation and tissue damage, particularly fibrosis in affected organs, such as the lungs." (PMID 40529303, 2025). "ICAM1 involves in the stimulation of immune response by promoting the adhesion and migration of leukocytes to the site of inflammation or infection." (PMID 39820173, 2025).
infection (continued). "Previous studies have demonstrated that TNF-α can stimulate endothelial cells to express adhesion molecules like VCAM-1 and ICAM-1 (Intercellular adhesion molecule-1), which are key to promoting inflammation during infection." (PMID 40431657, 2025). "With RV14 infections, all three receptors (PAFr, ICAM-1, and CEACAM-1) contributed to Hib adhesion, with CEACAM-1 playing a prominent role in bacterial adhesion." (PMID 40520162, 2025). "For RV14 infection, treatment with ICAM-1 and PAFr antibodies resulted in a slight decrease in bacterial adhesion, although these changes were not statistically significant." (PMID 40520162, 2025). "This heightened adherence of the parasite correlated with an increase in ICAM-1 expression on day 4 post-infection." (PMID 40298772, 2025). "We identified ICAM1 to be commonly upregulated in all three cell types upon ANDV infection, whereas it was only upregulated in two cell types (hPSC-CMs and -astrocytes) upon HTNV infection and only in hPSC-astrocytes upon SNV infection." (PMID 40857262, 2025). "Infection-induced microvascular inflammation dramatically elevated the sequestration of parasitized DCs, while treatments targeting the ICAM-1/CD18 leukocyte adhesion axis with blocking antibodies strongly reverted sequestration." (PMID 40229286, 2025). "Plasma concentration of intercellular adhesion molecule 1 was higher in unvaccinated compared to vaccinees in the first 9 days after infection." (PMID 41159782, 2025). "Infection triggers upregulation of adhesion molecules such as ICAM-1 and VCAM-1 on brain endothelial cells, promoting vascular permeability and inflammation." (PMID 40743275, 2025). "At three months post infection, hospitalized patients exhibited elevated levels of ICAM-1, VCAM-1, and IL-6, alongside a detectable immunoreactivity in SARS-CoV-2-specific T-cell response." (PMID 41226453, 2025). "T. cruzi infections also displayed upregulation of ICAM1 (CD54), which deficiency generates a higher infection susceptibility and a decrease in T cell recruitment." (PMID 39000601, 2024). "To investigate the relevance of the IFN-γ-mediated ICAM1 upregulation in the context of infection and to address the role of gC, we employed two recombinant, BAC-derived VZV pOka viruses: pOka-gC-GFP and pOka-ΔgC-GFP." (PMID 38909022, 2024). "This aligns with our observation of ICAM-1 trends, suggesting its potential role in indicating active infection." (PMID 39093864, 2024). "Meanwhile, compared to the RH strain (type I) tachyzoites, the ME49 strain (type II) showed significant early infectivity post-infection in bEnd.3 cells simultaneously stimulated the ICAM-1 overexpression and IL-6 and MCP-1 high secretion." (PMID 38073104, 2024). "This set included ICAM1, which was increased at the mRNA and protein levels in keratinocytes, facilitating Jurkat cell adhesion and resulting in better infection of both Jurkat cells and PBMCs." (PMID 38909022, 2024). "The CD11b+ cells were also the predominant cells migrating through the barrier upon infection with GFP+ tachyzoites (MOI=1) with upregulation of ICAM-1, enabling the leukocyte migration across endothelial barriers in the rat in vitro BBB model." (PMID 38073104, 2024). "As with ICAM1, CD11c surface protein expression on PMNs following exposure to both strains of Gc at 1 and 2h post-infection was measured by flow cytometry." (PMID 38976720, 2024). "ICAM-1 plays a vital role in the adhesion of leukocytes to endothelial cells during inflammation, facilitating immune cell trafficking to sites of infection or tissue damage." (PMID 39182041, 2024). "Most rhinoviruses initiate cellular infections by binding ICAM-1 and these rhinoviruses are categorized as major group rhinoviruses." (PMID 38473734, 2024).
infection (continued). "Seven differentially expressed genes (DDX58, STAT1, MX1, IRAK1, MAPK11, RELA, and ICAM1) were randomly selected and quantified using qRT-PCR to validate the differential expression observed in A549 cells using RNA-Seq across varying infection time points." (PMID 38673764, 2024). "It is possible that both Cd36 and Icam1 expression were altered in ceiling LECs by cytokines and chemokines expressed in the dLN in the first 5 days after infection, biasing our gating analysis." (PMID 38194268, 2024). "These pathogens use adhesion molecules such as platelet activating factor receptor (PAFR) and intercellular adhesion molecule-1 (ICAM–1) to gain cellular entry, causing infections." (PMID 38610892, 2024). "As a control, the RNA of host cells was extracted and analyzed for the expression of ICAM-1 upon infection." (PMID 37110443, 2023). "We found that during the acute phase of infection, ICAM1 transcript levels were significantly decreased at all time points following T. cruzi challenge." (PMID 36936778, 2023). "Rhinovirus induces expression of IL-1β in these cells, which drives further expression of ICAM-1, and this mechanism likely increases cell infectivity in the early stages of infection." (PMID 37237555, 2023). "Consistently, both cell lines produce different immune effectors in response to infection.Additionally, ICAM-1 expression in both cell lines is differentially induced by TGF-β1 and IFN-γ, suggesting a different modulation of susceptibility to infection." (PMID 36968102, 2023). "The production of ICAM-1 is induced by inflammation, such as occurs during infection, when one of its main functions is to direct white blood cells to the site of the infection." (PMID 37237555, 2023). "During RSV infection, chemoattractants like ICAM-1 and IL-8 produced by epithelial cells lead to the recruitment of neutrophils to the site of infection." (PMID 37896776, 2023). "CD11a interacts with ICAM-1 and has been previously used to identify Plasmodium-specific T cells responding to infection." (PMID 36993971, 2023). "The levels of IL-12p70, MCP-1, IL-10, IL-1β, IFN-γ, IL-2, M-CSF, VEGF, ICAM-1, and P-selectin increased after infection; however, the expression of all except MCP-1, IFN-γ, and P-selectin was strongly suppressed by anti-TNF-α Ab treatment." (PMID 37939119, 2023). "Monoclonal antibodies to ICAM-1 strongly inhibit the infection of primary human tracheal epithelial cell cultures." (PMID 37237555, 2023). "CVA11 infection caused extensive oncolytic activity in all three of the examined human NSCLC cell lines, with high intercellular adhesion molecule-1 (ICAM-1) expression associated with greater CVA11-induced cytotoxicity." (PMID 37046036, 2023). "There were also multiple endothelial markers that that were downregulated in severe infection including ICAM-1 (p = 0.02) and C-reactive protein (CRP) (p = 0.0003)." (PMID 37598150, 2023). "The γ3 peptide specifically binds to ICAM-1 at the infection sites, allowing γ3-RBCNPs to transport ciprofloxacin to the infection regions rather than accumulating in the kidneys." (PMID 37514085, 2023). "We previously reported that HBZ increases ICAM-1 expression in HTLV-1-infected cells to enhance the efficiency of infection." (PMID 36827461, 2023). "Coxsackievirus A21 (CVA21, Cavatak) is a non-enveloped virus with a single-stranded RNA genome with preferential infection of intercellular adhesion molecule 1 (ICAM-1)-expressing cells." (PMID 38006049, 2023).
infection (continued). "This assumption is supported by the enhanced expression of icam-1 in the single-sex infected groups after only 4 days of infection, since ICAM-1, as an endothelial activation marker, can also be associated with the wound healing process." (PMID 38133315, 2023). "The cell line panel expresses the PV (CD155) and CAV21 (ICAM1, CD54) receptors at levels mediating uniform susceptibility to infection." (PMID 37962360, 2023). "Given the immunofluorescence data supporting an increase in ICAM1 expression by leukocytes upon infection, we compared the numbers of ICAM1 expressing leukocytes in the blood." (PMID 35787830, 2022). "This study defines the function of LFA-1 and ICAM-1 in sustaining inflammatory NK cells during intracellular pathogen infection." (PMID 36206304, 2022). "Neuropathology score at day 6 post-infection of mice infected with T. congolense 1/148, treated with α-ICAM1 antibody or its isotype control (N=4–5)." (PMID 35787830, 2022). "As expected, prior to and shortly after infection the homing of transferred virus specific OT-II CD4+ T cells into ICAM-1/2-/- MedLNs was markedly impaired." (PMID 36895258, 2022). "Parasite load in the brain of WT or RAG2 KO mice, treated with either α-IgG2 or α-ICAM1 antibody, quantified by intravital microscopy, at day 6 post-infection." (PMID 35787830, 2022). "(A) Immunohistochemical (IHC) staining showed increased expression of endothelial VCAM-1 and ICAM-1 in the OB on day 6 of infection." (PMID 35510986, 2022). "In spite of this, IL-33 treatment increased permissiveness of MCs to HRV16 infection which, from the RNA-Seq data, we attributed to upregulation of ICAM1." (PMID 36366528, 2022). "In contrast, during IL3000 infections, ICAM1 expression increased in all brain regions with the exception of the hippocampus, hypothalamus, and medulla." (PMID 35787830, 2022). "To follow the fate of OT-I CD8+ T cell effectors generated in the ICAM-1/2-/- lung draining LNs in response to PR8-SIINFEKL infection, we next determined the accumulation of effector OT-I CD8+ T cells in the infected lung." (PMID 36895258, 2022). "Significantly increased expression of vascular cell adhesion molecule 1 (VCAM-1) and intercellular adhesion molecule 1 (ICAM-1) were found in the OB on day 6 of infection." (PMID 35510986, 2022). "We provide proof-of-concept that leukocyte ICAM-1 can contribute to the TEM of DCs in the context of infection." (PMID 35990682, 2022). "In IL3000 infections, we also observed an increase in ICAM1 expression by endothelial cells (p-value = 0.003)." (PMID 35787830, 2022). "Both NK-cell and CD49a+ NK-cell subsets are increased in ocular tissues, and the expression levels of LFA-1 in NK cells and ICAM-1 in the OT murine model were upregulated upon infection." (PMID 36206304, 2022). "We observed that, during 1/148 infections, expression of ICAM1 increased in all anatomic regions of the brain, with the exception of the hypothalamus." (PMID 35787830, 2022). "Strikingly, ICAM-1/2-/- mice normally recovered from infection, elicited potent humoral immunity, and generated long lasting cellular immunity to both homosubtypic and heterosubtypic variants of influenza A strains." (PMID 36895258, 2022). "In contrast, the total numbers of endogenous polyclonal GC B cells (Fas+, CD38low) recovered 12 days post infection were similar in WT and ICAM-1/2-/- MedLNs." (PMID 36895258, 2022). "To test if T. congolense sequestration depends on similar host molecules, we blocked ICAM1 in vivo, by administering α-ICAM1 antibody 24 hr before infection, repeating daily during the course of infection." (PMID 35787830, 2022). "In spite of this, when tested functionally this antiviral signature was insufficient to control HRV16 replication as IL-33 increased expression of ICAM1 which facilitated infection and increased viral replication in MCs." (PMID 36366528, 2022).